LRRC73 (leucine rich repeat containing 73)
Synonyms: C6orf154; dJ337H4.2
Tractability: PROTAC: its protein half-life has been measured.
Gene: Protein-coding gene on chromosome 6 (43,506,965 to 43,510,388, reverse strand). Ensembl gene ENSG00000204052.
Subcellular location (Human Protein Atlas): Cytosol; Nuclear bodies
Gene Ontology:
Molecular function: protein binding
Genetic constraint (gnomAD): Loss-of-function variants: 16 observed, 26.42 expected, observed/expected ratio (o/e) 0.61, 90% interval 0.41 to 0.92. The upper end of that interval is the gene's LOEUF score, 0.92, which puts it in group 3 of 6, group 1 being the genes least tolerant of losing a copy. Missense variants: 344 observed, 415.86 expected, observed/expected ratio (o/e) 0.83, 90% interval 0.76 to 0.9. Synonymous variants: 210 observed, 179.45 expected, observed/expected ratio (o/e) 1.17, 90% interval 1.04 to 1.31.
Homologues: Orthologues: macaque LRRC73 (100% identical), chimpanzee LRRC73 (99% identical), dog LRRC73 (99% identical), pig LRRC73 (99% identical), guinea pig LRRC73 (99% identical), mouse Lrrc73 (99% identical), rat Lrrc73 (98% identical), rabbit LRRC73 (92% identical), zebrafish lrrc73 (74% identical), tropical clawed frog lrrc73 (53% identical).